DSP (desmoplakin)
Diseases named in the same sentence as DSP in open-access papers (continued):
Sharing a sentence is not in itself a finding about the gene and the disease.
cancer (41 papers, 2002 to 2025). A tumor composed of atypical neoplastic, often pleomorphic cells that invade other tissues. "In line with its strong dAD result, desmosome dysregulation (including the obligate desmosome protein DSP) has been identified as a general early and causal event in cancer through murine experiments." (PMID 41188181, 2025). "Another study showed the palmitate-induced pathway driving the migration of the cancer cells through the loss of desmoplakin mediated by activation of the IRE1-XBP1 pathway and zinc finger E-box binding homeobox transcription factors." (PMID 36619574, 2022). "Accordingly, abnormal localization and loss of desmoplakin were shown to correlate with progression in several types of cancer including HCC." (PMID 32977498, 2020). "Like desmoplakin, periplakin’s loss of expression has also been affiliated with the development and progression of cancer, specifically, bladder, colon, and esophageal squamous cell carcinoma cancers." (PMID 29373494, 2018). "It was also shown that desmoplakin expression was reduced in metastatic oropharyngeal cancers, and that desmoplakin (II) expression, a product of alternative splicing, in these cancers was associated with a poor clinical outcome." (PMID 29373494, 2018). "The single cancer GWAS/meta-analysis found five risk variants of the specific individual cancers across East Asians and Europeans (e.g., PADI6 on 1p36 and DSP on 6p24)." (PMID 37340002, 2023). "Other studies have reported different roles of DSP in cancer, but it is generally clear that it is a key factor in the EMT." (PMID 34249924, 2021). "In response to the high ATP level inside the cancer cells relative to healthy cells, DSP disassembled and released the loaded doxorubicin preferentially in cancer cells, in parallel it also displayed strong fluorescence and ultimately induced apoptosis." (PMID 34307293, 2021). "Epigenetic regulation of DSP and its ability to increase the sensitivity to apoptosis of cancer therapy have important implications for clinical application." (PMID 32498335, 2020). "In parallel with the migration assay, we conducted a Matrigel invasion assay to elucidate the impact of zyxin, nesprin-1, and desmoplakin on the invasive behaviors of HCT-116 cancer cells." (PMID 31501460, 2019). "DSP displays significant overexpression in cancers in 26 datasets and downexpression in 24 datasets." (PMID 29587367, 2018). "Desmoplakin (DSP) is required for functional desmosomal adhesion which has been linked to cancer cells development and progression in several cancers." (PMID 28650955, 2017). "Although desmoplakin and dystroglycan are commonly down-regulated in clinical cancer specimens, they were overexpressed in our study." (PMID 12402156, 2002). "For example, DSP is related to the growth and metastasis of cancer cells." (PMID 36138770, 2022). "In addition, the disruption of desmosome-KIF interactions by the expression of a dominant negative mutant of desmoplakin decreases both cell-cell and cell-substrate forces in epithelial carcinoma cells." (PMID 36200046, 2022). "Reduced expression of DSP has been noted to increase invasion and metastasis in several cancers." (PMID 34001250, 2021). "Alterations in the expression or function of DSP may affect desmosome assembly and signal transduction of cancer cells, which may promote tumorigenesis." (PMID 34203070, 2021). "To assess this hypothesis, we engineered into the oncogene-expressing cancer cells in RT2 mice a genetic deletion of desmoplakin (Dsp; MGI: 109611), an intracellular protein critical for desmosomal stability." (PMID 20862307, 2010). "However, EMT in cancer involves downregulation of the expression of desmosomal, adherens/tight junction and cytolinker proteins such as E-cadherin, occludens, claudins, EpCAM, α6β4 integrin, different cytokeratins, DSP, PPL." (PMID 34001250, 2021).
cancer (continued). "Five of the inherited variants in genes associated with cancer or actionable for hereditary diseases have been described in the literature as pathogenic (MUTYH: c.933+3A > C) or of unknown significance (APC, APOB, DSG2, DSP)." (PMID 30233642, 2018). "For example, EAS-specific unambiguous probes (n = 484) from the HM450K array were overlapped with promoters and gene bodies of 140 cancer driver genes, such as CTNNB1, DSP, FRK, HLA-A, NOX4, and TRIO." (PMID 40445831, 2025). "To further verify the validity of the data, we used the GEPIA database to validate the expression of DSP, PPP1R13L and ANXA8 in human cancers and normal cervix." (PMID 38952985, 2024). "To further verify the validity of the data, we used GEPIA database to validate the expression of DSP, PPP1R13L and ANXA8 in human cancers and normal cervix." (PMID 38952985, 2024). "Anti-cancer-activity-related proteins were altered, including CLTA, HSPA9, HIST2H2BF, KRT18, HINT1, DSP, and VIM." (PMID 37371778, 2023). "In our study, desmoplakin knockout significantly reduced p-JNK, suggesting a different mechanism for various cancer cell lines, although further investigation is needed." (PMID 31501460, 2019). "Whereas E-cadherin, P-cadherin and DSP were completely displaced from cell–cell junctions in SJG15 cells, they exhibited a largely normal localisation in other cancer cells." (PMID 22541538, 2012). "Moreover, we used GEPIA database to validate the expression of DSP, PPP1R13L and ANXA8 in human cancers and normal cervix." (PMID 38952985, 2024). "However, six proteins influenced cancer cell survival in the COS–GA group in previous studies, with downregulated HSPA9 and HIST2H2BF and upregulated KRT18, HINT1, DSP, and VIM proteins." (PMID 37371778, 2023). "For the purposes of the microarray data validation, we have randomly selected 3 of all the genes that may play the most important role in the cancer cells-CAFs interactions: PCDH19, DSP and MAG." (PMID 22453032, 2012).
cardiac disease (14 papers, 2011 to 2026). "We aimed to evaluate the clinical manifestations of cardiac disease associated with variants in DSP through a genotype-first approach employed in the University of Pennsylvania Center for Inherited Cardiovascular Disease registry." (PMID 35083019, 2022). "We hypothesize that the predominantly right ventricular phenotype-first approach utilized to date to investigate DSP-associated cardiac disease has limited the identification of important clinical features and outcomes." (PMID 35083019, 2022). "Emerging data from ACM cohorts have suggested features of DSP-associated cardiac disease that may be distinct from DCM, ARVC, and ALVC." (PMID 35083019, 2022). "A substantial number of genetic variants in the genes DSP, JUP, DSC2, KLHL24 and GJA1 have been reported to underly skin and/or cardiac disease." (PMID 36142674, 2022). "A Japanese study on 9 cases of SUDEP performed next-generation sequencing to examine 73 genes related to inherited heart disease: the Authors found KCNE1 as pathogenic variants (together with KCNE1) and also 3 other potentially pathogenic variants (MYH6, DSP, DSG2) according to in silico analysis." (PMID 41062843, 2026). "Mutations in desmosomal genes have been observed in 50% of patients with arrhythmogenic heart disease, and these are represented by mutations in the genes for Plakophilin C (PKP2), Desmoplakin (DSP), Desmocollin-2 (DSC2), Desmoglein-2 (DSG2), and Plakoglobin (JUP)." (PMID 40361967, 2025). "Different genes have been found to be related to ALVC, and the more frequent are Desmoplakin (DSP), Filamin C (FLNC), Phospholamban (PLN), and Desmin (DES); however, there is a prevalence of variants of genes already known to be related to inherited cardiac disease and of gene-elusive cases." (PMID 35893404, 2022). "Preservation of partial desmoplakin function may explain the absence of cardiac disease in SFWHS while still producing significant epidermal and hair shaft instability." (PMID 41502835, 2026). "Notably, truncating variants in genes such as TTN, FLNC, DSP, PKP2, and MYH7 were frequently reported, particularly in young decedents with no significant history of cardiac disease." (PMID 41374444, 2025).
cardiovascular disease (9 papers, 2016 to 2024). "In the current study, through targeted next generation sequencing platform covering a board rang of inherited cardiovascular disease genes, a novel frame-shift variant DSP c.832delG is identified in a large SCD family." (PMID 32046637, 2020). "Overall, we identified 5 reportable variants classified as KP or EP in the DSP, MYH7, and FBN1 genes, which have been reported to cause different types of cardiovascular diseases." (PMID 30217213, 2018). "For example, a total of 18 genes related to cardiovascular diseases are identified to be closely related to PM2.5, and cardiovascular disease relevant gene DSP is significantly related to PM2.5 gene JUP." (PMID 27243032, 2016). "We screened 404 genes related to inherited cardiovascular disease and confirmed that no deleterious mutations were present in other desmosomal genes, including DSC2, DSG2, JUP, and DSP, involved in the etiology of AC." (PMID 35063130, 2022).
infection (4 papers, 2019 to 2023). The state of being infected such as from the introduction of a foreign agent such as serum, vaccine, antigenic substance or organism. "Novel EMT proteomic biomarkers (keratins 2, 6A and 20, collagen 12A1, desmoplakin) and inflammatory biomarkers (PSMB9, FGL2) were associated with early infection and barrier dysfunction." (PMID 36639424, 2023). "In addition, we have observed that other proteins involved in promoting or inducing apoptosis, such as DSP, PAK2, and heat shock protein family A (Hsp70) member 8 (HSPA8) proteins, were highly upregulated in rock bream RBCs upon RBIV infection." (PMID 30886611, 2019).
genetic disease (2 papers, 2022 to 2025). "Numerous other disease-associated mutations have been documented throughout the desmoplakin (DSP) gene resulting in inherited diseases that affect the heart and skin." (PMID 35008956, 2022).
myopathies (2 papers, 2020 to 2022). "In addition, recent reports have suggested desmoplakin (DSP) related myopathies may be distinct from other ACM cases." (PMID 32466575, 2020).
neurodegenerative disease (2 papers, 2021 to 2023). A disorder of the central nervous system characterized by gradual and progressive loss of neural tissue and neurologic function. "Proteome-based assessment of plasma biomarkers in 511 subjects with AD along with other neurodegenerative diseases and normal older people showed that DSP was upregulated in the AD group." (PMID 34931130, 2021).
DSP also shares sentences with these, for which no sentence is quoted: acute myocarditis (7 papers); hypertrophic cardiomyopathy (5); familial dilated cardiomyopathy (4); woolly hair syndrome (4); Brugada syndrome (3); cardiac arrhythmias (3); catecholaminergic polymorphic ventricular tachycardia (3); ectodermal dysplasia (3); metastatic melanoma (3); skin fragility (3); bullous pemphigoid (2); Duchenne muscular dystrophy (2); epidermolytic palmoplantar keratoderma (2); hepatocellular carcinoma (2); hereditary cardiomyopathies (2); Hypertension (2); joint diseases (2); keratosis palmoplantaris striata II (2); long QT syndrome 3 (2); myocardial disease (2); Nail dystrophy (2); palmoplantar keratosis (2); right ventricular cardiomyopathies (2); Adams-Oliver syndrome 5 (1); adenocarcinoma (1); adult-onset Still disease (1); allergies (1); Alopecia universalis (1); atrial fibrillation (1); atrial tachycardia (1).
A further 78 diseases each share a sentence with DSP in 1 paper.